UMOD (uromodulin)
Diseases named in the same sentence as UMOD in open-access papers (continued):
Sharing a sentence is not in itself a finding about the gene and the disease.
diabetes (20 papers, 2012 to 2025). "Diabetes progression to kidney damage reduces eGFR and as eGFR declines the excretion of uromodulin follows the same trend." (PMID 39888908, 2025). "In a previous study, one of these 29 endogenous peptides, “SGSVIDQSRVLNLG-PITR” (uromodulin peptide) showed decreased expression in diabetes, suggesting its potential relevance in disease states." (PMID 39051237, 2024). "Urinary extracellular vesicle uromodulin mRNA levels exhibited a gradual increase from type 2 diabetes mellitus to DKD groups, showing a correlation with commonly used diagnostic criteria such as eGFR and ACR." (PMID 37835820, 2023). "Various studies have indicated that urinary uromodulin is initially normal following a diabetes diagnosis and then progressively increases with diabetes duration." (PMID 37835820, 2023). "Various studies have reported increased uromodulin excretion in the urine of adults with type 1 diabetes, particularly in the early stages of diabetes (duration < 15 years)." (PMID 37835820, 2023). "In participants with diabetes mellitus, urinary uromodulin levels were significantly lower in those with diabetic nephropathy compared to those with normal kidney function." (PMID 31065383, 2019). "Lower serum and plasma uromodulin levels are also found to be associated with decreased kidney function in subjectively healthy elderly (>60 years) patients without diabetes." (PMID 36556931, 2022). "Albuminuria, urine NGAL, transferrin, IgG, and uromodulin correlated with diabetes control." (PMID 30158836, 2018). "Moreover, urine albumin, uACR, urine NGAL and NGAL/creatinine ratio, urine transferrin, urine IgG, urine uromodulin, and uromodulin/creatinine ratio significantly correlated with diabetes control as reflected by HbA1c concentrations." (PMID 30158836, 2018). "The IgA–uromodulin complex might be a marker of IgAN in a similar way as HbA1c in diabetes; however, the mechanism and the meaning where such a complex is formed are problems that are still uncertain, and needs to be clarified in the future." (PMID 22415778, 2012). "In contrast to NGAL, urinary uromodulin could not be associated with eGFR, eGFR changes, or albuminuria, and its only significant association was with markers of diabetes control." (PMID 37298105, 2023). "We investigated the association of distal tubule markers, epidermal growth factor (EGF) and uromodulin (UMOD), with DKD progression in the Veterans Affairs Diabetes in Nephropathy (VA NEPHRON-D) clinical trial.METHODS." (PMID 40548378, 2025). "Further, upregulation of UMOD has also been described in early diabetes mellitus with hyperfiltration lacking morphological visible glomerular injury, and in sepsis." (PMID 40087735, 2025). "Uromodulin (UMOD) demonstrated the most significant change, increasing by 3.19-fold in the case of diabetes, while envoplakin (EVPL) showed the most substantial decrease in the case of diabetes." (PMID 40142159, 2025). "However, in individuals with longstanding diabetes (>15 years) or advanced diabetic kidney disease (DKD), urinary uromodulin levels tended to decline." (PMID 37835820, 2023).
kidney damage (19 papers, 2017 to 2025). "Reduced levels of urinary uromodulin indicate kidney damage or a loss of kidney function and are associated with adverse outcomes." (PMID 39937009, 2025). "In a study by Kules focusing on the hemoprotozoal parasite Babesia canis, which causes kidney dysfunction in dogs, they used both SDMA and uromodulin as markers of kidney damage." (PMID 39061561, 2024). "Representative missense mutations in the UMOD gene causing ADTKD differentially drive the formation of mutant uromodulin aggregates, impacting on kidney damage and disease progression." (PMID 37885358, 2023). "Importantly, this risk variant directly enhances uromodulin expression in a dose-dependent manner, leading to salt-sensitive hypertension and kidney damage in both mice and humans." (PMID 37835820, 2023). "Some Umod risk variants could increase uromodulin expression and then induce salt-sensitive hypertension and kidney damage." (PMID 35308536, 2022). "However, in the setting of abnormal kidney function/kidney damage, the decline in absolute uromodulin excretion was caused by the reduction in functional nephron mass and/or reserve of the tubules." (PMID 30454063, 2018). "Consequently, lower uromodulin levels in PE could reflect an increased susceptibility to vascular and kidney damage that could associate with the adverse long-term cardiovascular and kidney outcomes of this population." (PMID 38500759, 2024). "On the opposite, post-partum urinary uromodulin levels are markedly lower in PE patients as compared to healthy controls, potentially reflecting an increased susceptibility to vascular and kidney damage that could associate with adverse long-term cardiovascular and kidney outcomes." (PMID 38500759, 2024). "Additional evidence of kidney damage is provided by the consistent reduction of uromodulin fragments." (PMID 39762268, 2025). "The main driver of kidney damage in FJHN is believed to be the pathological accumulation of mutant uromodulin protein." (PMID 37835820, 2023). "The measurement of urinary uromodulin levels can offer valuable insights into the extent of kidney damage in both active SLE and CKD cases, providing clinicians with an additional tool for assessing kidney health and disease progression." (PMID 37835820, 2023). "Uromodulin is a pleiotropic and overall protective protein, leading us to expect compensatory upregulation upon kidney damage to fulfill its protective role." (PMID 37835820, 2023). "Collectively, these data indicate that the two Umod KI lines present typical manifestations of ADTKD‐UMOD, with allelic and gene‐dosage effects on uromodulin processing and severity of kidney damage, in line with observations in humans." (PMID 37885358, 2023). "With regard to the ESKD events, our results only found a trend of improvement in the discriminating ability after inclusion of serum uromodulin in the model with traditional markers for kidney function and kidney damage." (PMID 30454063, 2018). "Experimental data from Trudu showed that over-expression of uromodulin leads to salt-sensitive hypertension, left ventricular hypertrophy and kidney damage." (PMID 30454063, 2018). "Alternatively, a reverse causality can be postulated and the occurrence of PE itself could lead to a rapid decrease in uromodulin levels as a reflection of ongoing kidney damage." (PMID 38500759, 2024). "Urinary proteome analysis of Fabry treatment-naive patients revealed an increased expression of uromodulin, which could potentially play a role in kidney damage at the tubular level, as well as contribute to inflammation and immune responses within the kidney." (PMID 37835820, 2023). "Therefore, it is suggested that in the case of kidney damage, uromodulin is upregulated and contributes to the repair and regeneration processes." (PMID 37835820, 2023). "Uromodulin may be a potential urinary biomarker of the renal tubular reserve function in male and female Fabry patients with nephropathy." (PMID 35722479, 2022).
kidney damage (continued). "These might include TGF-b1, CD80, podocalyxin, podocin, nephrin or uromodulin as nephropathy related biomarkers, and S1P or IL-18 as biomarkers more related to cardiomyopathy." (PMID 33924567, 2021). "The role of uromodulin as a biomarker of kidney injury was recently reviewed, concluding that serum uromodulin levels represent a valuable early predictor of renal, primarily tubular damage and that lower concentrations have a prognostic role in predicting the progression of kidney damage." (PMID 36556931, 2022). "It was suggested that uromodulin up-regulation could be considered a very early marker of kidney damage at the tubular level, in cases with a normal level of creatinine and normal GFR, especially in heterozygous female Fabry patients, that may associate the normal value of α-Gal A activity." (PMID 35722479, 2022). "Our study further explored the potential biomarkers of kidney damage in plasma and showed significant differences in the levels of cystatin C, TFF3, and uromodulin between patients with progressive nephropathy and their control subjects." (PMID 39937009, 2025). "Together, these analyses indicate the crucial role of uromodulin aggregates in driving the induction of ER stress and UPR, and the extent of kidney damage." (PMID 37885358, 2023). "The lower values of uromodulin excretion (1st tertile) corresponded to cases without significant kidney damage and favorable outcomes." (PMID 37835820, 2023). "However, this second hypothesis seems less likely as we could not detect differences in uromodulin levels between PE patients with or without kidney damage." (PMID 38500759, 2024).
diabetic nephropathy (17 papers, 2013 to 2025). "In recent years, researchers have conducted more and more large‐scale GWAS and Mendelian randomization analysis to explore the genetic variation related to diabetes nephropathy, including UMOD, COL4A3, COL20A1, TENM2, SLC47A1, and so forth." (PMID 40931579, 2025). "Electron microscopic study showed features supportive for the diagnosis of diabetic nephropathy and distinctive concentric appearance of vancomycin tubular casts within the fibrillary background of uromodulin." (PMID 31871855, 2019). "In other renal disease, such as autosomal polycystic kidney disease, glomerular nephritis and diabetic nephropathy, urinary uromodulin excretion is obviously decreased." (PMID 23990922, 2013). "EGF and UMOD are two urine biomarkers that we found predict progression of diabetic kidney disease." (PMID 40548378, 2025). "Indeed, in our previous study, the expression levels of SLC12A1 and UMOD were significantly different between diabetic nephropathy patients and healthy volunteers (presented in American Society of Nephrology in November 2012)." (PMID 25275511, 2014). "We profiled two mouse models of disease, early diabetic kidney disease (DKD, BTBR ob/ob) and uromodulin autosomal dominant tubulointerstitial kidney disease (ADTKD, UMOD-KI)." (PMID 35069263, 2021).
gout (16 papers, 2017 to 2025). A condition characterized by painful swelling of the joints, which is caused by deposition of urate crystals. "In the present study, we reported for the first time that UMOD hypermethylation was significantly associated with the risk of gout in Chinese male patients." (PMID 28894234, 2017). "The family history, suggesting autosomal dominant inheritance, and the associated early-onset gout with FE of urate prompted genetic testing for UMOD mutations." (PMID 28605509, 2017). "In the current study, elevated UMOD methylation in peripheral blood was shown to be associated with the risk of Gout, which is characterized by urate crystal-induced inflammation." (PMID 28894234, 2017). "Here we report an exceptional case of ADTKD in a consanguineous family who presented with early-onset gout and renal disease with a novel homozygous mutation in UMOD (p.C120Y)." (PMID 28605509, 2017). "UMOD hypermethylation is significantly associated with gout risk in Chinese male patients." (PMID 41311848, 2025). "Additional studies have shown that gout is associated with UMOD gene mutations." (PMID 41311848, 2025). "The study found that the methylation level of UMOD in peripheral blood was related to the risk of gout, and its methylation evaluation could predict the risk of gout." (PMID 35922835, 2022). "UMOD hypermethylation was significantly associated with the risk of gout." (PMID 28894234, 2017). "Previous study showed that gout was associated with UMOD gene mutations." (PMID 28894234, 2017). "In conclusion, our study found that UMOD DNA hypermethylation in peripheral blood might be used to predict the risk of gout." (PMID 28894234, 2017). "In addition, homozygous mutations in UMOD gene seem to be more prone to early-onset gout." (PMID 35922835, 2022). "Urinary regulin glycoprotein (UMOD) is a methylation-dependent protein, and due to its high methylation status, its expression is higher in gout patients than in control groups." (PMID 41311848, 2025). "Uromodulin (UMOD) encodes an uromodulin glycoprotein, and its mutation results in uromodulin glycoprotein dysfunction and the occurrence of gout." (PMID 28894234, 2017). "In addition to epidemiological topics such as blood pressure, heart failure, dietary patterns, and gout, biomarkers and genes such as urine 6-bromotryptophan, serum uromodulin, GWAS of urate and gout, telomere length, and other biomarkers and genes have been actively investigated." (PMID 34374903, 2022). "Therefore, we supposed that UMOD methylation might play a potential role in the occurrence of gout." (PMID 28894234, 2017).
familial juvenile hyperuricemic nephropathy (15 papers, 2005 to 2024). "ADTKD-UMOD is defined by the presence of a heterozygous pathogenic variant in UMOD gene, encoding uromodulin, in hereditary tubulointerstitial kidney diseases." (PMID 29569962, 2018). "Mutations in the UMOD gene, encoding for uromodulin, also known as Tamm-Horsfall protein, are responsible for a rare autosomal dominant form of tubulointerstitial kidney disease referred as ADTKD-UMOD." (PMID 28437467, 2017). "In addition, rare UMOD mutations have been identified in patients diagnosed with familial juvenile hyperuricemic nephropathy (FJHN), medullary cystic kidney disease 2 (MCKD2), and autosomal dominant tubulointerstitial kidney disease (ADTKD)." (PMID 37835820, 2023). "MEDLINE and Chinese Biomedicine Databases were searched with ‘uromodulin’, ‘juvenile gout’ and their related terms." (PMID 29569962, 2018).
kidney failure (15 papers, 2013 to 2026). An acute or chronic condition that is characterized by the inability of the kidneys to adequately filter the blood. "Mutations in the UMOD gene cause intracellular localization of UMOD protein and drive one of the most common familial forms of kidney failures, autosomal dominant tubulointerstitial kidney disease (ADTKD)." (PMID 40198127, 2025). "Probands from 12 apparently unrelated pedigrees with a family history of kidney failure within a geographically contiguous UK region were shown to be heterozygous for a pathogenic variant of UMOD c.278_289delTCTGCCCCGAAG insCCGCCTCCT." (PMID 36038257, 2023). "Monoallelic mutations in the UMOD gene cause autosomal dominant tubulointerstitial kidney disease (ADTKD-UMOD), an incurable genetic disorder that leads to kidney failure." (PMID 39680459, 2024). "UMOD mutations can invariably lead to CKD and kidney failure." (PMID 37835820, 2023). "In this study, we report a rare UMOD variant, c.278_289delTCTGCCCCGAAG insCCGCCTCCT detected in a cluster of unrelated families within a contiguous geographical area with unexplained CKD leading to kidney failure." (PMID 36038257, 2023). "Elevated uromodulin expression alone does not directly lead to kidney failure." (PMID 37835820, 2023).
end-stage renal disease (12 papers, 2012 to 2025). "UMOD polymorphism rs12917707 is known to associate with end stage renal failure of mixed aetiologies." (PMID 25163389, 2014). "Low urinary uromodulin levels have been shown to predict the development of CKD over 9 to 10 years of follow-up, and the rapid decline in renal function in CKD patients leads to progression to end-stage renal disease within 1 year." (PMID 40332103, 2025).
renal fibrosis (10 papers, 2015 to 2026). A final common manifestation of a wide variety of chronic kidney diseases characterized by glomerulosclerosis and tubulointerstitial fibrosis. "Thus, we have developed a novel mouse model for renal fibrosis, which will be a valuable resource to decipher the mechanisms linking uromodulin mutations with ER stress and renal fibrosis." (PMID 28325753, 2017). "Reduced extracellular secretion or abnormal structure of uromodulin appears to be a critical factor contributing to the development of renal fibrosis." (PMID 41531277, 2026). "We observed a dynamic decrease in uromodulin and CFH protein levels, which were associated with the development of renal fibrosis and C3 deposition." (PMID 37047611, 2023). "Heterozygous and homozygous mutant mice developed reduced uric acid excretion, renal fibrosis, immune cell infiltration and progressive renal failure, with decreased maturation and excretion of uromodulin, due to its retention in the ER." (PMID 28325753, 2017). "Fibrinogen, a glycoprotein involved in inflammation, and uromodulin, a kidney-specific protein, were shown to participate in renal fibrosis." (PMID 26431327, 2015). "An extremely diminished level of uromodulin correlated with severe renal fibrosis." (PMID 37047611, 2023). "Although endoplasmic reticulum stress, cell damage and apoptosis induced by the accumulation of mutant uromodulin have been identified as pathogenic mechanisms in ADTKD‐UMOD, additional findings suggest that other mechanisms may also contribute to renal fibrosis." (PMID 41531277, 2026).
renal failure (9 papers, 2013 to 2022). "Since, in addition, cholesterol efflux capacity adjusted for eGFR or uromodulin was invariably associated with CVD mortality, we conclude that cholesterol efflux is not a mediator of adverse cardiovascular outcomes in renal insufficiency." (PMID 36009383, 2022).
urolithiasis (9 papers, 2009 to 2025). Stone(s) within the urinary tract. "Inheridate progressive kidney diseases, which are related to mutations of the UMOD gene, reveal low to very low uromodulin concentrations even before the decline in eGFR, progressive renal papillary calcification, and urolithiasis, and are at risk to develop UTI and ESKD." (PMID 35106269, 2021). "This could have impact for diseases such as urolithiasis where the urinary levels of uromodulin may be directly correlated with its protective function." (PMID 26673890, 2015). "Second, there is evidence that uromodulin is involved in regulating urinary stone formation." (PMID 19529781, 2009). "For a long time uromodulin had been rather overlooked by medical professinals but recent researches showed that the levels of uromodulin in plasma and urine are valuable biomarkers of kidney and urinary tract diceases including chronic kidney dicease, urolithiasis, and some genetic disorders." (PMID 33917374, 2021).